PTH (parathyroid hormone)
Diseases named in the same sentence as PTH in open-access papers (continued):
Sharing a sentence is not in itself a finding about the gene and the disease.
adenoma (continued). "PTx should be considered in patients with adenoma or in resistant patients with elevated serum Ca and PTH levels despite cinacalcet treatment." (PMID 32913586, 2020). "Age, sex, body mass index (BMI), pre- and postoperative serum calcium, creatinine, 25(OH)D levels, PTH at baseline (PTH T0), and PTH at 10 minutes after adenoma resection (PTH T10) were recorded." (PMID 32256573, 2020). "Typically, during parathyroidectomy, peripheral blood samples collected prior to incision, at incision and 5, 10 and 15-min post incision where a 50% decline in PTH indicates successful adenoma resection." (PMID 33139830, 2020). "Other authors report a significant correlation between adenoma weight and PTH-decrease at 10 min postexcision." (PMID 33256695, 2020). "It is unclear how much PTH contributes the adenoma but there is evidence suggesting stronger correlation between PTH and adenoma weight in extreme levels of PTH." (PMID 33256695, 2020). "Long-term stimulation results in increased parathyroid hormone (PTH) secretion and parathyroid hyperplasia or even adenoma." (PMID 33059621, 2020). "When the PTH level is below 6 pmol/l (57 pg/ml) the adenoma is likely to weigh < 400 mg, whereas PTH levels > 170 pg/ml usually indicate an adenoma weight > 800 mg." (PMID 33256695, 2020). "Ten minutes after the adenoma removal, the median and interquartile values of PTH (PTH T10) were 24.1 pg/mL (16.8–37.91 pg/mL) (range 3.3–172 pg/mL) for PTH 2G and 12.3 pg/mL (8.4–19.2 pg/mL) (range 4–119 pg/mL) for PTH 3G." (PMID 32256573, 2020). "There was a moderate correlation between the serum calcium level and adenoma weight (r = 0.40) and volume (r = 0.41), and a strong correlation was found between the PTH level and weight (r = 0.69) and volume (r = 0.72)." (PMID 31367807, 2019). "Patients with normal levels of PTH had smaller adenomas with low bone turn-over and preserved bone density and glomerular filtration rate compared with the patients with overt PHP." (PMID 31074404, 2019). "Intraoperative PTH (ioPTH) monitoring confirmed the excision of the adenoma as the PTH dropped from the initial pre-excision level of 546 ng/L to 239 ng/L 10 minutes after the excision, and then to 161 ng/L 20 minutes after excision, a 70% drop." (PMID 31722742, 2019). "From our literature review, we conclude that GPTA generally presents symptomatically, with high preoperative PTH and serum calcium directly proportional to the adenoma weight." (PMID 31722742, 2019). "Sestamibi uptake is related to the activity of adenoma cells, which explains the correlation between localization accuracy and PTH level." (PMID 31427650, 2019). "In this reported case, possibilities of parathyroid hyperplasia or adenoma were excluded based on an ultrasound examination of the parathyroid and laboratory tests revealing normal serum calcium, phosphate, and parathyroid hormone levels." (PMID 29390266, 2017). "It was reported that patients from Turkey had higher serum PTH levels, more severe bone disease and larger adenomas." (PMID 28251020, 2017). "A significant correlation between sestamibi scan, PTH levels, and adenoma volume was observed only in patients with solid adenomas." (PMID 29183364, 2017). "The PTH concentration taken 1 hour after the adenoma had been removed confirmed a level within the normal range." (PMID 26881146, 2016). "We also analysed Ki-67 expression in benign adenomas concentrating on different preoperative biochemical features including Ca and PTH serum levels." (PMID 26658808, 2016). "PTH decline <30 %, product P (minimal PTH concentration (pg/mL) × maximal calcium concentration (mg/dL)) > 1100, and ratio R (relative PTH decline/relative calcium increase) < 4 diagnosed adenoma with specificity of 100, 90 and 100 %, respectively." (PMID 26542689, 2015).
adenoma (continued). "Serial intraoperative PTH (IOPTH) measurement has now been adopted by most institutions to gauge appropriate decrease in serum PTH levels, usually a 50% or greater decrease relative to preoperative values, following excision of an adenoma." (PMID 25629056, 2015). "Characteristically, it has a faster progression and higher PTH and calcium levels along with a higher prevalence of renal and pancreatic disease than adenomas." (PMID 25276444, 2014). "Serum samples were collected 20 minutes after removal of the adenoma/parathyroid gland(s) and PTH levels were compared with preoperative values." (PMID 25241609, 2014). "After removal of the adenomas (weight: 4,400 (#1) and 985 mg (#2), respectively), PTH decreased within 10 minutes into the normal range: 89.3 (#1) and 59.2 pmol/L (#2) before excision versus 5.7 (#1) and 2.5 pmol/L (#2) ten minutes after resection." (PMID 24758398, 2014). "We believe that the global elevation of intraoperative PTH from all sites is likely secondary to persistent PTH levels, as compared to the 100-fold gradient normally seen between venous samplings that confirms localization of the adenoma intraoperatively." (PMID 24381775, 2013). "Intraoperative venous sampling of PTH during four-gland exploration can be an adjunct to 4DCT in the lateralization of an adenoma." (PMID 24381775, 2013). "The Spanish patients had higher preoperative levels of PTH (13.5 versus 11.0 pmol/L, P < 0.001), urinary calcium (7.3 versus 4.1 mmol/L, P < 0.001), and heavier adenomas (620 versus 500 g, P < 0.001)." (PMID 23986777, 2013). "Monitoring of the PTH decay appeared to be influenced by surgical manipulations during the more difficult adenoma preparation in minimally invasive parathyroidectomy." (PMID 24044556, 2013). "The new standard for most surgeons is preoperative radiologic localization of adenomas to direct a focused parathyroidectomy using unilateral neck exploration and adjunctive intraoperative PTH." (PMID 21747852, 2011). "Unilateral neck exploration is also highly effective, because PTH has a short half-life of less than five minutes and can be measured after and before adenoma resection to ensure that the culprit gland has been removed." (PMID 21747852, 2011). "Curative resection was established by monitoring intact serum PTH levels after excision of the adenoma." (PMID 22091358, 2011). "Removal of the second adenoma was followed by the expected fall in serum PTH concentration of >50% confirming successful surgery." (PMID 21197437, 2010). "In our case series, Intraoperative serum PTH level quantification had higher sensitivity (100%) in detecting the parathyroid pathology (single or double adenoma) compared to each imaging technique alone." (PMID 21197437, 2010). "Failure of serum PTH to appropriately decrease after excision of a single adenoma should raise suspicion of additional adenomas and the surgical approach should be modified accordingly, if necessary by converting MIP to a standard full neck exploration." (PMID 21197437, 2010). "The weight of the adenoma plays an important role in the accuracy of this test as well as the preoperative PTH level." (PMID 20844661, 2010). "PTH levels are markedly elevated in patients with parathyroid carcinoma and only slightly elevated in those with adenomas." (PMID 19016595, 2008). "Despite persistently elevated calcium and PTH levels, all diagnostic imaging was negative for parathyroid hyperplasia and adenoma." (PMID 41502796, 2026). "However, the relationship between the PTH-WO level and adenoma size remains controversial in the literature." (PMID 41036141, 2025). "Interestingly, the lack of significant PTH level difference between ectopic and orthotopic (left/right) adenomas contradicts the common assumption that ectopic adenomas would demonstrate higher PTH levels due to delayed diagnosis." (PMID 40445316, 2025). "Intraoperative PTH was measured before surgery and after the excision of the adenoma." (PMID 40445316, 2025).
adenoma (continued). "The positive relationship between adenoma size and plasma PTH levels in PHPT cases is well known." (PMID 41036141, 2025). "Our findings demonstrate that adenoma size and the presence of cystic components significantly influence PTH-WO levels, emphasizing the importance of incorporating these morphological parameters into the interpretation of test results and clinical decision-making." (PMID 41036141, 2025). "Our study revealed important differences in PTH level based on adenoma location." (PMID 40445316, 2025). "On the other hand, the value of NIRAF during focused parathyroidectomy guided by intraoperative PTH for a single adenoma may be diminished." (PMID 40668552, 2025). "In our study, the rate of adenomas with irregular margins and heterogeneous echogenicity was higher than in previous studies, indicating that atypical features are more frequent in cases undergoing PTH-WO." (PMID 41036141, 2025). "Furthermore, we did not detect a statistically significant influence of resected adenoma volume on the size of PTH and total calcium levels reduction on the first day after surgery." (PMID 39941666, 2025). "This phenomenon has been described in patients with large adenomas or markedly elevated baseline PTH levels, in whom physiological decline may lag behind the 10-minute sampling window." (PMID 41393630, 2025). "Moreover, since all adenomas were PTH-WO positive and surgically confirmed, we were unable to perform receiver operating characteristic analysis to determine diagnostic thresholds by lesion size." (PMID 41036141, 2025). "Indeed, a cohort of 378 PHPT cases showed a significant positive correlation of both preoperative calcium and PTH values with adenoma dimensions and weight." (PMID 39831932, 2025). "Additionally, a positive correlation was identified between PTH-WO levels and the short and long axis dimensions of the adenomas." (PMID 41036141, 2025). "Of the 159 patients, all had preoperative PTH and calcium levels available, 134 had weight recorded on pathological data and 128 patients had sufficient data available to calculate an ellipsoid volume of the adenoma." (PMID 40979160, 2025). "The PTH levels are about 5 to 10 times higher or approximately > 500 mg/dL in carcinoma, whereas in adenomas, they may be within normal limits or mildly increased." (PMID 40612282, 2025). "The Spearman correlation analysis revealed that PTH-WO values increased with adenoma size." (PMID 41036141, 2025). "Depending on these factors, there may be differences between the cases with PHPT living in different geographical regions with regard to parameters, such as age, bone findings, blood PTH and vitamin D levels, and the adenoma size." (PMID 40332255, 2025). "Although a ≥ 50% drop from baseline (blood sampling before induction) in serum PTH levels 10 min after removal of the adenoma is generally considered as adequate, this interpretative criterion of I.O. PTH is characterized by false-positive results in case of multiglandular disease." (PMID 38622315, 2024). "Notably, PTH level and PTH-derived PFi correlate with adenoma size, making parathyroid hormone a more reliable predictor of the disease than calcium levels or vitamin D levels." (PMID 39040613, 2024). "The pattern of relationship between adenoma weight and serum PTH level (with similar slopes but with different intercepts) supports our hypothesis." (PMID 36817587, 2023). "In the low baseline PTH group, two patients had a double adenoma." (PMID 37627880, 2023). "The PTH levels significantly differed between the adenoma and hyperplasia groups (P < .001)." (PMID 37713846, 2023). "PTH/Svol is related to the functional load of the entire adenoma and is a novel measurable parameter that could possibly be composed of cross-sectional imaging and a functional hormonal marker." (PMID 37892003, 2023).
adenoma (continued). "The pathological examination confirmed 51 (78.5%) single adenomas, six patients with (9.2%) double adenomas, four patients (6.2%) with diffuse hyperplasia and four (6.2%) without pathological parathyroid tissue (but normalized postoperative PTH and calcemic response)." (PMID 37174047, 2023). "Also, the relative slopes of regression lines suggests that larger tumors secrete relatively less PTH/g adenoma weight than smaller adenomas." (PMID 36817587, 2023). "This hypothesis was confirmed by an in vitro study, which found that cells from larger glands released PTH at a lower rate than those from smaller adenomas." (PMID 37892003, 2023). "In the high-PTH group, five patients had a double adenoma, and one patient had three adenomas." (PMID 37627880, 2023). "Although previous research has investigated associations of adenoma magnitude and PTH measurements with the radiopharmaceutical uptake, the PTH/Svol has not been previously surveyed." (PMID 37892003, 2023). "Furthermore, increased PTH mRNA expression was found in 1% of adenomas in that series and in parathyroid carcinomas and atypical adenomas." (PMID 35038313, 2022). "The secondary objectives of this study are (i) to investigate the diagnostic efficacy of [18F]fluorocholine PET/CT depending on the level of PTH and (ii) to demonstrate a significant difference and cut-off between adenomas and hyperplasias regarding the defined quantitative criteria." (PMID 35983092, 2022). "In other studies, PTH mRNA was reported to be increased in human adenomas relative to normal glands, PTH content was decreased and circulating (serum) PTH was increased These findings are compatible with augmented newly synthesized PTH, minimal storage and rapid secretion." (PMID 35038313, 2022). "Large adenomas are more likely with higher PTH, higher calcium, and lower phosphate levels." (PMID 33928428, 2021). "In these cases, the decision to terminate surgery was made by an experienced surgeon considering preoperative localization studies, macroscopic presentation of the adenoma, histopathologic features in fresh frozen sections during surgery, and extent of PTH decline." (PMID 33993327, 2021). "Serum PTH levels reflect adenoma and normal parathyroid gland PTH output." (PMID 33256695, 2020). "The third‐/second‐generation PTH ratio is a new tool trying to distinguish carcinoma from adenoma." (PMID 32884778, 2020). "Therefore, several authors recommend that very high levels of PTH should alarm the surgeon of the possible existence of a too large adenoma." (PMID 33256695, 2020). "Following variables were analyzed: preoperative serum calcium, phosphorus and parathormone, intraoperative parathormone before and after adenoma excision, intraoperative PTH decrease, postoperative serum calcium and parathormone (PTHpostop—pg/ml), calcium and PTH decrease." (PMID 33256695, 2020). "The patient underwent parathyroidectomy of the adenomas which normalised his PTH and Ca levels." (PMID 31797261, 2020). "Serum calcium levels, PTH and calcium decrease correlate only weak with adenoma weight." (PMID 33256695, 2020). "For instance, PTH levels rise above ~ 500 pg/mL during hyperfunctioning adenoma while post-surgical excision of the hyperfunctioning gland, PTH levels may drop upto ~ 20 pg/mL." (PMID 33139830, 2020). "We found MET-PET/CT seems to predict MGD in patients with large size and high weight PTH adenomas." (PMID 31223506, 2019). "Furthermore, increased direct secretion of PTH is thought to occur through the development of adenoma or hyperplasia; hypocalciuria likely arises through the inhibition of renal cyclic adenosine monophosphate (cAMP)." (PMID 29260296, 2018). "However, there was no meaningful difference between other laboratory and histopathological findings (i.e. serum calcium and PTH levels, and weight of adenoma) between these two groups." (PMID 29516131, 2018).
adenoma (continued). "However, there was no meaningful difference in other laboratory and histopathological findings including serum calcium and PTH or the weight of the adenomas between these two groups." (PMID 29516131, 2018). "After removing the adenoma the PTH marked a decrease from the initial value to 57 pg/ml." (PMID 30317121, 2018). "After removing the adenoma, the PTH marked a decrease from initial (398 pg/ml) value to 57 pg/ml." (PMID 30317121, 2018). "Also, and most important, normalization of serum calcium and PTH levels was reported to follow surgical treatment of patients with aldosterone-producing adenomas as well as treatment with spironolactone of patients with bilateral adrenal hyperplasia." (PMID 29056965, 2017). "Parathyroid hormone levels in adenomas typically don’t exceed three times the normal upper limit." (PMID 29354025, 2017). "In support of the close interplay existing between PTH and aldosterone, recent evidence indicates that type-1 PTH receptors are expressed in aldosterone-producing adenomas and explains why PTH elevation might increase aldosterone secretion." (PMID 29056965, 2017). "There is also a positive correlation between initial presenting PTH level andweight of adenoma (correlation coefficient 0.53), while there is a weakly negative correlation between initial presenting calcium level and weight of adenoma (correlation coefficient −0.37)." (PMID 28003924, 2016). "However, there is a positive correlation between initial presenting PTH level and size of adenoma on pathological examination (correlation coefficient 0.71)." (PMID 28003924, 2016). "All atypical adenomas (n = 4) and carcinomas (n = 6)investigated expressed PTH and PTH mRNA." (PMID 26865585, 2016). "Higher serum calcium (P = 0.014) and PTH (P = 0.055) concentrations and larger tumours (P < 0.001) characterized the 206 patients with a positive preoperative scan who were cured by removal of a single adenoma." (PMID 25722888, 2015). "With a high PTH the surgeon needs to seek another adenoma or parathyroid hyperplasia." (PMID 24716007, 2014). "Interestingly, venous sampling from the second exploration before showed elevated intraoperative PTH levels within a similar location to where the occult adenoma was in the chest." (PMID 24381775, 2013). "The clinical presentation of parathyroid carcinomas and adenomas can be very similar, although patients with parathyroid carcinoma register significantly higher serum calcium, parathyroid hormone (PTH) and alkaline phosphatase levels compared with patients with adenomas." (PMID 20181049, 2010). "There have also been several reports of false-positive phenomena in cases of multiple gland pathology including double adenomas, and combination adenoma and hyperplasia, wherein the PTH level decreases to within the normal range, but begins to increase post-operatively." (PMID 16504029, 2006). "Higher PTH levels in this group may be related to the higher volumes of removed adenomas." (PMID 40810066, 2025). "Additionally, in normal gland cells of patients with adenomas, both the set point and maximum PTH secretion at low Ca concentrations were found to be significantly lower compared to the normal glands of patients with normal Ca homeostasis (glands sampled during thyroidectomy)." (PMID 40810066, 2025). "However, biochemical parameters such as markedly elevated calcium (>3.5 mmol/L) or PTH levels may raise suspicion for carcinoma, although overlap with adenoma frequently occurs." (PMID 41523514, 2025). "Furthermore, as adenoma volume increases, PTH and calcium levels also rise." (PMID 40104290, 2025). "However, in our study, we found a correlation between PTH and Ca levels and adenoma volume." (PMID 40104290, 2025).